TRPV4 (transient receptor potential cation channel subfamily V member 4)
Diseases named in the same sentence as TRPV4 in open-access papers (continued):
Sharing a sentence is not in itself a finding about the gene and the disease.
breast carcinoma (continued). "The known role of EMT in the development of therapeutic resistance provides another dimension to TRPV4 inhibition for the treatment of some breast cancers, the feasibility of which is demonstrated by the clinical trials of TRPV4 inhibitors for heart failure." (PMID 33322037, 2020). "TRPV4 was an important component of the calcium influx phase induced in MDA-MB-468 breast cancer cells by the EMT inducer epidermal growth factor (EGF)." (PMID 33322037, 2020). "In summary, TRPV4 is a receptor-selective regulator of activated calcium influx in breast cancer cells that overexpress TRPV4 and pharmacological activation of TRPV4 is sufficient to induce EMT in these cells." (PMID 33322037, 2020). "Basal-like breast tumors have elevated levels of TRPV4; however, the expression of TRPV4 within this breast cancer subtype is heterogeneous." (PMID 33322037, 2020). "Pharmacological activation of TRPV4 then drove the induction of a variety of EMT markers in breast cancer cells." (PMID 33322037, 2020). "Given the indirect association between TRPV4 expression and EMT in breast cancer and the importance of Ca2+ signaling in EMT, we sought to assess the possible role of TRPV4 in EMT induction." (PMID 33322037, 2020). "Another TRPV channel involved in regulation of breast cancer cell angiogenesis and migration is TRPV4." (PMID 32825277, 2020). "Evidence from endothelial cells (ECs) derived from human breast carcinomas suggests that arachidonate-induced intracellular Ca2+ signals mediated by TRPV4 contribute to tumour angiogenesis." (PMID 32825277, 2020). "In contrast to TRPC6, TRPV4 is positively regulated pronounced cell death through apoptosis, oncosis, or necrosis in breast cancer or melanoma cells." (PMID 31189890, 2019). "TRPV4 accelerates actin dynamics by promoting F-actin depolymerization, thereby contributing to reduced cell stiffness of breast cancer cells." (PMID 31275168, 2019). "Conversely, exogenous expression of TRPV4 in breast cancer cells accelerates actin dynamics and is correlated with a higher activation of cofilin, a protein that promotes the severing of actin filaments." (PMID 31275168, 2019). "The functions of TRPV4 protein from breast cancer-derived endothelial cells are similar to those of normal endothelial cells." (PMID 31235786, 2019). "In breast cancer, TRPV4 overexpression leads to cancer cell softening, increased cell blebbing and actin reorganization." (PMID 29772843, 2018). "Accordingly, TRPV4 should be inhibited to halt tumor vascularization in breast cancer, while it must be stimulated to normalize tumor vasculature in LLC." (PMID 29324706, 2018). "This has been well documented for TRPV4 channels in breast cancer and prostate cancer-derived endothelial cells." (PMID 29772843, 2018). "In breast cancer, TRPV4 plays a role in cell migration and metastasis via Ca2+-dependent remodeling of the actin cytoskeleton." (PMID 30223530, 2018). "Collectively, the data support the role of AKT as a mediator of TRPV4 signaling and transendothelial migration of breast cancer cells." (PMID 28530703, 2017). "Here, we showed that TRPV4 is overexpressed in breast cancer tissues and its expression correlates with poor outcomes." (PMID 28530703, 2017). "Here, we elucidated the molecular mechanisms mediated by TRPV4 in the metastatic breast cancer cells." (PMID 28530703, 2017). "TRPV4 is overexpressed in the basal subtype of breast cancer, most of which are aggressive and triple-negative in nature." (PMID 27291497, 2016). "Next, we investigated the effect of exogenous expression of TRPV4 on human breast cancer metastasis." (PMID 27291497, 2016). "The qPCR data also revealed heightened Trpv4 transcripts in 4T0 and 4T1 compared to 67N breast cancer cells." (PMID 27291497, 2016). "Herein, the functional roles and mode of action of TRPV4 in migration, invasion and extravasation of breast cancer cells were investigated." (PMID 27291497, 2016).
breast carcinoma (continued). "Overall, overexpression of TRPV4 in MB468 cells conferred physical softness to breast cancer cells via decreasing scaffolding by cell cortex proteins and increasing G to F actin ratio." (PMID 27291497, 2016). "Using mass spectrometry, we identified TRPV4 as a crucial component of this pathway, providing insights into how non-invasive breast cancer cells may evolve into invasive phenotypes under mechanical stress." (PMID 40256993, 2025). "Interestingly, TRP agonists also showed antitumor effects, with the TRPV4 agonist GSK1016790A reducing breast cancer cell viability, and endogenous overexpression of TRPV4 was evident in vitro, leading to reduced tumor growth in vivo." (PMID 38505262, 2024). "TRPV4 expression is deregulated in various cancers, including breast carcinomas." (PMID 38514727, 2024). "In addition, knockdown of TRPV4 decreases breast cancer cell migration and invasion, while overexpressing TRPV4 facilitates actin depolymerization and decreases cellular stiffness." (PMID 37864030, 2023). "As for TRPV4, researchers found that TRPV4 could promote breast cancer metastasis by regulating cell extravasation, stiffness, and actin cortex." (PMID 37730669, 2023). "Additionally, administration of 4α-PDD (agonist of TRPV4) downregulated adhesion−related tumor suppressor genes in 4T07 (mouse breast cancer cell line)." (PMID 36830651, 2023). "Moreover, TRPV4 activation in human breast cancer (4T07) cells enhances Akt and FAK phosphorylation and transendothelial migration." (PMID 36158191, 2022). "Furthermore, pharmacological activation of TRPV4 is sufficient to trigger EMT of breast cancer cells." (PMID 36619170, 2022). "Moreover, it has been proven that TRPV4 reinforces malignancy extravasation in breast cancer and serves as a predictor of poor clinical outcomes in some solid epithelial malignancies." (PMID 34669779, 2021). "Furthermore, TRPV4 directly regulates Ca2+ influx and increased cell migration of metastatic breast cancer cells." (PMID 32843668, 2020). "Given that overexpressed TRPV4 is sufficient to generate softening of cell cortex and an increase in invasion in breast cancer cells, this last mechanism may play an important role in the observed gain of invasion." (PMID 32186440, 2020). "Moreover, a recent study implied that TRPV4 drives breast cancer cell and breast tumor-derived endothelial cell migration." (PMID 32843668, 2020). "Another study showed TRPV4 regulates breast cancer cell migration by increasing cell deformability." (PMID 32843668, 2020). "Particularly, activation of TRPV4 induces both cell death and metastasis in breast cancer cells." (PMID 32211326, 2020). "Moreover, elevated TRPV4 expression was predominately found in a specific subset of basal molecular breast cancer and that TRPV4 activation led to reduced tumor growth." (PMID 31189890, 2019). "Breast cancer cells in which TRPV4 is activated undergo cytoskeletal remodeling." (PMID 31235786, 2019). "There are numerous studies showing a clear correlation between cancer patient survival and TRP channel expression, e.g., TRPC1, TRPM2 and TRPV4 in breast cancer, TRPM7 in PDAC, TRPM8 in bladder cancer and osteosarcoma and TRPV2 in breast and esophageal cancer to name just a few examples." (PMID 29772843, 2018). "TRPV4 was physiologically gated by AA, which is quite abundant in breast cancer microenvironment." (PMID 29324706, 2018). "It was suggested that TRPV4 activation thereby regulates breast cancer cell extravasation." (PMID 29772843, 2018). "To investigate whether TRPV4 has a role in clinical breast cancer, we performed immunohistochemistry (IHC) to examine the TRPV4 protein expression between the normal and the cancerous tissues." (PMID 28530703, 2017). "However, more in-depth studies will clarify the clinical utility of TRPV4 for breast cancer management." (PMID 28530703, 2017).
breast carcinoma (continued). "Finally, we also showed that TRPV4 has a clinical implication on the aggression of breast cancer and survival rate in the breast cancer patients." (PMID 28530703, 2017). "In conclusion, TRPV4 may regulate breast cancer metastasis by regulating cell softness through the Ca2+-dependent AKT-E-cadherin signaling axis and regulation of the expression of extracellular proteins." (PMID 28530703, 2017). "The data indicates relevance of Talin expression levels with metastatic breast cancer and supports the notion that TRPV4 and Talin may cooperate to promote cancer metastasis." (PMID 28530703, 2017). "Unlike other TRP superfamily channels, its role in cancers are unknown until recently when we reported TRPV4 to be required for cancer cell softness that may promote breast cancer cell extravasation and metastasis." (PMID 28530703, 2017). "In summary, our data show that TRPV4 contributes to breast cancer metastasis." (PMID 27291497, 2016). "TRPV4 may be exploited as a drug target for management of triple negative, metastatic breast cancers." (PMID 27291497, 2016). "Overexpression of TRPV4 promoted breast cancer cell softness, blebbing, and actin reorganization." (PMID 27291497, 2016). "Endothelial cells derived from breast cancer vessels contain high levels of TRPV4, and inhibition of TRPV4 inhibits the stimulated migration of endothelial cells derived from breast cancer, suggesting that pharmacological inhibition of TRPV4 can inhibit angiogenesis." (PMID 40078961, 2025). "Our further assessment of basal-like breast cancers suggests that TRPV4 may contribute to or correlate with more invasive disease, given its association with poorer relapse-free survival in LN+ basal breast cancers but not LN-." (PMID 33322037, 2020). "All in all, more efforts are required to precisely understand the molecular mechanism of TRPV4 in either enhancing tumor cell death or cytoskeleton reorganization, which might provide potential strategies for treating breast cancers by targeting TRPV4 in the future." (PMID 32211326, 2020). "This may be reflective of less TRPV4 expression in PMC42LA breast cancer cells." (PMID 33322037, 2020). "Interestingly, the expression of TRPV4 is correlated with poor clinical outcomes in breast cancers." (PMID 32211326, 2020). "TRPV4 may be a viable drug target for management of metastatic breast cancers." (PMID 27291497, 2016). "In contrast, other invasive breast cancer cell lines, such as MDA-MB-231 cells, exhibited opposing responses to TRPV4 inhibition and activation, highlighting the heterogeneity of TRPV4 roles in invasive cancer progression." (PMID 40256993, 2025). "TRPV4 activation induces the expression of EMT markers such as vimentin, Snail, AXL, SERPINE1, and CD44 both in normal mammary epithelial and breast cancer cells." (PMID 39517820, 2024). "Additionally, breast cancer cells and extravasating leukocytes have similar expression of specific phosphorylated proteins necessary for actin cytoskeletal remodeling and deformability, which suggests the importance of TRPV4 for the phosphorylation of these proteins in extravasation." (PMID 34831037, 2021). "Our assessment of Ca2+ influx induced by a variety of stimuli demonstrated the differential contribution of TRPV4 to sustained Ca2+ influx induced by the purinergic receptor activator ATP, the PAR2 activator trypsin, and EGF in MDA-MB-468 breast cancer cells." (PMID 33322037, 2020). "TRPV4 silencing significantly attenuated the accumulated distance traveled of single MDA-MB-468 breast cancer cells." (PMID 33322037, 2020). "Activating TRPV4 by using arachidonic acid can significantly promote the migration of endothelial cells derived from human breast cancer, but not that of normal human microvascular endothelial cells, which may be ascribed to the significantly higher expression of TRPV4 in breast cancer." (PMID 31235786, 2019).
breast carcinoma (continued). "Comparing to Srsf3 WT liver cancer, Srsf3 KO significantly increases Sox4, E2f1, Trpv4, Trim6, and Myc expression, but does not so in Erbb2 breast cancer." (PMID 40568073, 2025). "Further studies show that the expression of TRPV4 in breast cancer cells lead to the actin reorganization and therefore promotes breast cancer cell softness and tumor invasion without affecting cell proliferation." (PMID 32211326, 2020). "Our studies highlight new roles for TRPV4 in breast cancer and identify that some ion channels are not just regulators of specific elements of EMT but can be the driver of this phenomenon." (PMID 33322037, 2020). "So far, TRPV1, TRPV4 and TPRV6 have been well-studied in breast cancers progression." (PMID 32211326, 2020). "MDA-MB-468 breast cancer cells where TRPV4 activation produced robust induction of EMT have high levels of TRPV4, in contrast to PMC42LA cells where TRPV4 levels are substantially lower and where TRPV4 activation produced far more modest and less diverse induction of EMT markers." (PMID 33322037, 2020). "Though TRPV1, TRPV4, and TRPV6 all mediate calcium fluxes in breast cancer cells, their unique and even opposite functions in breast cancer progression suggest a complicated network of calcium signaling in modulation of tumor cell functions, which requires further efforts to elucidate." (PMID 32211326, 2020). "TRPV4 knockdown decreases migration, invasion, and transendothelial migration, but not the viability, of breast cancer cells in vitro as well as the number of metastatic lung nodules in vivo." (PMID 31275168, 2019). "Addition of the TRPV4 agonist GSK1016790A in MDA-MB-468 breast cancer cells loaded with FLIPR Calcium 4 no-wash dye, BD Calcium Assay Kit, or fluo-4 with quenchers or washing led to a concentration-dependent increase in intracellular calcium." (PMID 30856233, 2019). "TRPV4 was shown to be required for breast cancer cell invasion and transendothelial migration but not growth/proliferation." (PMID 27291497, 2016). "This is consistent with the previous observation that knock-down of TRPV4 did not affect proliferation of mouse 4T07 breast cancer cells." (PMID 27291497, 2016). "Another study revealed that TRPV4 might regulate cell softness and extracellular matrix protein expression through the Ca 2+ dependent AKT-E-cadherin signal axis, thus regulating metastasis of breast cancer." (PMID 35558077, 2022). "Furthermore, we exploited selective TRPV4 pharmacological inhibition and activation to define the role of TRPV4 in EMT induction and to determine if activation of a specific calcium-permeable ion channel is sufficient to induce EMT in breast cancer cells." (PMID 33322037, 2020). "Therefore, TRPV4 might represent a novel and specific target to treat breast cancer as it is only barely expressed and does not drive migration in healthy endothelial cells." (PMID 29324706, 2018). "Whether TRPV4 contributes to the biology of breast cancer epithelial cells is not known." (PMID 27291497, 2016). "Unlike TRPV1 and TRPV4, TRPV6 has been shown to positively promote breast cancers progression." (PMID 32211326, 2020). "Till now, though not as much as those reported in breast cancer cells and osteoclasts, multiple calcium channels have also been reported to modulate osteoblast proliferation, differentiation, migration and mineralization, including TRPV1, TRPV4, TRPM7, TRPP2, Cav1.2, ORAI1/SOCE, P2X1, and P2X7." (PMID 32211326, 2020).
Hypertension (31 papers, 2012 to 2025). The presence of chronic increased pressure in the systemic arterial system. "The proposed importance of TRPV4 to endothelial Ca2+ entry and changes in vascular disease have resulted in the channel being linked to the vascular changes in hypertension." (PMID 39440451, 2025). "Transient receptor potential vanilloid 4 (TRPV4) channels have been associated with numerous pulmonary pathologies, including hypertension, asthma, and acute lung injury." (PMID 39451235, 2024). "Growing evidence supports involvement of these channels in shear stress and agonist-mediated endothelial signaling, and changes in TRPV4 signaling are linked to disease states including hypertension, diabetes and pulmonary edema." (PMID 35492608, 2022). "Such decoupling of TRPV4 and KCa2.3 channels has been implicated in vascular dysfunction associated with hypertension." (PMID 35492608, 2022). "It was recently reported that blocking Piezo1 or TRPV4 prevented hypertension-associated vascular hyperpermeability, but the underlying mechanisms or possible interactions were not uncovered." (PMID 33298523, 2021). "Altered TRPV4 signaling has recently been implicated in various cardiovascular diseases, including hypertension and atherosclerosis." (PMID 32235694, 2020). "Diabetes and atherosclerosis are associated with loss of functional endothelial TRPV4 channels, and multiple animal models of hypertension have recently been linked to loss of interaction between TRPV4 and KCa2.3 channel subunits." (PMID 32235694, 2020). "More recently, it was reported that an impairment of the physical and functional interaction of TRPV4-SKCa channels underlies the reduced EDH-mediated responses in small arteries from mice with hypertension induced by a high-salt diet." (PMID 29361737, 2018). "In particular, we sought to determine whether changes in endothelial function that occur in hypertension were associated with redirection of TRPV4 responses." (PMID 39440451, 2025). "The modified physical forces raise the possibility that altered TRPV4-mediated Ca2+ influx may be a component of the endothelial changes that are associated with hypertension." (PMID 39440451, 2025). "Next, we sought to elucidate the mechanisms underlying TRPV4-mediated responses in hypertension." (PMID 39440451, 2025). "Notably, endothelial transient receptor potential vanilloid 4 (TRPV-4) channels are associated with hypertension, as they regulate Ca2+ concentrations." (PMID 35370628, 2021). "This mini review therefore focuses on the pathophysiological role of the TRPV4 channel in endothelial dysfunction associated with cardiovascular disease (CVD) risk factors such as hypertension, obesity, diabetes mellitus and ageing, along with its underlying mechanisms." (PMID 34616307, 2021). "In addition, emerging evidence reveals that the decrease in EDH-mediated responses in hypertension is accompanied by a loss of function and/or expression of endothelial TRPV4 channels." (PMID 29361737, 2018). "Our hypothesis is that high-intensity exercise training (HIET) could produce high lactic acid that may aggravate renal inflammatory conditions and activate TRPV4-TGFβ1-Smad2/3-CTGF-mediated renal fibrotic pathways in hypertension, which might cause adverse effects (renal damage and fibrosis)." (PMID 36160854, 2022). "The altered priority of the slow and rapid types of Ca2+ signal in hypertension can itself be explained by changes in the expression of TRPV4 and IP3 receptors." (PMID 39440451, 2025). "In hypertension, the oscillations have prominence at lower levels of activation, whereas the sustained slow component dominates at higher levels of TRPV4 activity." (PMID 39440451, 2025). "Specifically, endothelial cell TRPV4 channels play a dual role in modulating blood vessel function in hypertension." (PMID 39440451, 2025). "Our results help reconcile the contradictory proposals by highlighting two responses to TRPV4 activation in hypertension." (PMID 39440451, 2025).